CDK12 (cyclin dependent kinase 12)
Diseases named in the same sentence as CDK12 in open-access papers (continued):
Sharing a sentence is not in itself a finding about the gene and the disease.
cancer (continued). "Moreover, cancers with CDK12 mutations are often sensitive to PARP inhibitors - and preclinical and biological data from patients with PCa showed that CDK12 inactivation is related to increased burden of neoantigens, which can in turn enhance the immunogenicity." (PMID 35222436, 2022). "Thus, CDK12 inhibitors could be used in combination with DNA-damaging agents in HR-deficient cancers." (PMID 34771669, 2021). "Aberrant CDK12/13 signaling enhances translation of oncogenic transcripts, linking transcriptional control to protein synthesis reprogramming in cancer." (PMID 41491919, 2026). "The following subsections outline cancer-type-specific patterns of CDK12/13 alteration, functional consequences, and pharmacologic implications." (PMID 41491919, 2026). "The dysfunction of CDK12 and CDK13 has been linked to cancer progression and therapy resistance, making them promising targets for new therapeutic agents." (PMID 41491919, 2026). "Under cancer-associated stress conditions, increased CTD phosphorylation by CDK12/13 sustains oncogenic transcriptional programs and maintains survival under replication stress." (PMID 41491919, 2026). "By controlling cancer stem cells (CSCs) or influencing the genes required to activate downstream pathways such as ErbB-PI3K-AKT (Protein Kinase B) or WNT-signaling cascades, CDK12 facilitates cancer progression." (PMID 40361480, 2025). "Several CDKs, such as CDK4, CDK7, CDK9, and more recently CDK12, have been closely studied for their involvement in cancer progression." (PMID 40996961, 2025). "Through literature searches and cell line database queries, we were not able to identify any cancer models with de novo CDK12BAL, and only one prior study where a stable CDK12 deletion in a cancer cell line was generated." (PMID 39071291, 2025). "Blocking CDK12/13 boosts immune response against cancer by activating STING, helping immunotherapy work better—offering a new way to treat more patients effectively." (PMID 40955658, 2025). "In conclusion, CDK12 plays diverse roles that highlight its potential as a prognostic marker and therapeutic target for a range of human cancer types." (PMID 39800748, 2025). "To identify key components involved in MHC-I upregulation via CDK12/13 antagonism, we knocked out Cgas, Sting1 (encoding STING), Ifnar1 (encoding IFNAR1), or Rela (encoding p65) in cancer cell lines." (PMID 40955658, 2025). "Cdk12-null cancers developed increased DNA damage and lymphocytic immune infiltration—both in keeping with prior pathological analysis of human tumors." (PMID 40504161, 2025). "Based on our findings, it is plausible that various cancers exhibit distinct metabolic requirements induced by CDK12." (PMID 40996961, 2025). "As anticipated, knockout (KO) of Cgas, Sting1, or Ifnar1 abolished MHC-I induction by CDK12/13 antagonism in various cancer models." (PMID 40955658, 2025). "Three common and fundamental hallmarks of cancer, such as genome instability, epigenetic reprogramming and cancer stem cell self-renewal, are cellular processes in which the involvement of CDK12/13 has been demonstrated." (PMID 39533070, 2025). "The role of CDK12/13 as oncogenes in a MYC-overexpressed context has been highlighted in other cancer models." (PMID 39533070, 2025). "Loss or dysregulation of CDK12 leads to impaired DDR and genomic instability, a hallmark of aggressive cancers." (PMID 39806366, 2025). "The specific contribution of the CDK12 paralog gene CDK13 in cancer remains inadequately understood." (PMID 39800748, 2025). "Mechanistically, CDK12 inhibitors primarily exert their anticancer effects by enhancing the anti-aggregation effect in cancer cells, reducing Pol II CTD Ser2 phosphorylation to inhibit DDR gene expression, and synergizing with poly (ADP-ribose) PARPi5,14,16." (PMID 38503865, 2024). "We identified 6 patients of co-mutations in the CDK12 and RAD51C genes across various cancer types among 67,083 cancer patients in the cBioPortal database." (PMID 38953104, 2024).
cancer (continued). "For instance, in metastatic CRC, NCT02 acts as a molecular colloid that induces the ubiquitination and proteasomal degradation of cyclin K (CCNK) and its partner CDK12, leading to apoptosis of cancer cells." (PMID 38485957, 2024). "On the other hand, IR events induced by CDK12/13 inhibition were shown to enhance vulnerability of cancer cells to chemotherapeutic treatments." (PMID 38413979, 2024). "Our unbiased screening to search drug compounds for treating CDK12 mutated cancer cells led to identifying dihydro‐rotenone as the most efficient candidate, confirming the connection between ETC and CDK12." (PMID 38736108, 2024). "Monitoring CDK12 expression and intervening in early-stage cancer has significant implications for diagnosing cancers and improving patient outcomes." (PMID 38503865, 2024). "In this study, we used a broader range of cancer types to investigate the significance of early monitoring of CDK12 expression in cancer diagnosis and prognosis." (PMID 38503865, 2024). "Depletion or loss of function of the CDK12/13/CCNK complex induces DNA damage through reduced expression of DDR genes and inhibits cell proliferation in cancer cells." (PMID 39353441, 2024). "In 20 types of cancer, CDK12 expression was upregulated compared to that in normal samples, whereas CDK12 was downregulated in ACC, OV, THCA, UCEC, and UCS compared with normal tissues." (PMID 38503865, 2024). "Previous studies have indicated that CDK12 is involved in promoting the development of various cancers, including THCA, BRCA, LIHC, READ, and STAD5–9,22,23." (PMID 38503865, 2024). "The ability to convert existing kinase inhibitors into degraders of key regulatory proteins like cyclin K opens new avenues for therapeutic intervention in cancers driven by dysregulated CDK12 activity." (PMID 39450271, 2024). "Our findings have potential implications for the development of new therapeutic approaches targeting CDK12 in cancer treatment." (PMID 38503865, 2024). "YJ1206 represents a promising orally bioavailable CDK12/13 degrader developed as a therapeutic agent for cancer treatment." (PMID 39353441, 2024). "In contrast, other DNA damage response and repair genes, including BRCA1, BRCA2, ATM, BRIP, POLQ, and CDK12, were significantly more often mutated in CDX2-suppressed cancers." (PMID 39452477, 2024). "Cell cycle-dependent protein kinase 12 (CDK12) plays a key role in a variety of carcinogenesis processes and represents a promising therapeutic target for cancer treatment." (PMID 38503865, 2024). "Knockdown of either CDK12 or CDK13 had no discernible effects on cell proliferation, underscoring the necessity of inhibiting both CDK12/13 function to suppress cancer cell growth." (PMID 39353441, 2024). "Together, we conclude that inhibition of CDK12 induces expression of genes downstream of important pathways in cancer, wherein P-TEFb plays a key role." (PMID 37811895, 2023). "Although the effect of PP-C8 on cancer cells was similar to Cyclin K or CDK12 depletion, the in vivo metabolic stability of this drug was not examined." (PMID 37626854, 2023). "Our study establishes the mechanistic underpinning for combinatorial targeting of CDK12 with either P-TEFb or the induced oncogenic pathways in cancer." (PMID 37811895, 2023). "In turn, the CDK12-targeted cancer cells became hypersensitive to sub-lethal doses of selective inhibitors of P-TEFb." (PMID 37811895, 2023).
cancer (continued). "CDK12/13 activity is particularly important in cells with high transcriptional rate, such as cancer cells harboring MYC amplification or up-regulation." (PMID 37599362, 2023). "Together, SR-4835 seems to be a promising inhibitor for selectively targeting Cdk12 and shows promise for future cancer therapy applications." (PMID 38016516, 2023). "The role of CDK12/13 inhibitors as anti-cancer therapeutic agents is well known, but this is the first study to explore the use of CDK12/13 inhibitors in overcoming osimertinib resistance." (PMID 37190191, 2023). "While this activity is likely to occur genome-wide, inhibition or ablation of CDK12 function was shown to prevalently affect expression of DDR genes and to cause DNA repair defects, hence sensitizing different types of cancer cells to PARPi." (PMID 37202753, 2023). "Their research revealed that the CDK12/13 inhibitor SR4835 induced the immunogenic cell death of cancer cells by elevating endoplasmic reticulum stress and promoting dendritic cell activity." (PMID 37626854, 2023). "Our results show that inhibition of CDK12 stimulates P-TEFb and induces genes downstream of important cancer signaling pathways, which renders cancer cells highly sensitive to P-TEFb inhibitors." (PMID 37811895, 2023). "While down-regulation of DNA repair genes in CDK12-targeted cancer cells is being explored therapeutically, little is known about mechanisms and significance of transcriptional induction upon inhibition of CDK12." (PMID 37811895, 2023). "Cyclin dependent kinases 12 and 13 (CDK12/13) are promising therapeutic targets in human cancers, including HGSOC." (PMID 37202753, 2023). "With respect to genes CDK12 (CRKRS), CWC25 (CCDC49), GRB7, MIEN1 (C17orf37), PNMT and SIRT3, they have been shown to be linked to HER2 receptor and cancer." (PMID 37096121, 2023). "Transcriptome analyses revealed cancer-relevant genes whose expression is repressed by dual CDK12/13 inhibition through impaired splicing." (PMID 37202753, 2023). "Cyclin-dependent kinase-12 has recently gained more interest in PARP inhibitor resistance owing to its inactivating somatic alterations that have been found in various cancers." (PMID 35873570, 2022). "The germline variants R3008H and R805X in ATM as well as the substitution P1275L in CDK12 correlated with cancer familiarity." (PMID 35347810, 2022). "As the RAS/MAPK pathway is frequently hyperactivated in cancer, our results suggest that increased CDK12 activity provides a proliferative advantage to cancer cells." (PMID 36309522, 2022). "CDK12 was the most common co-amplification gene with ERBB2 in cancers with a high frequency of ERBB2 amplifications." (PMID 35911441, 2022). "This study is one of the few pan‐cancer analyses of CDK12 alterations demonstrating that CDK12 alterations are rare events across different cancer types." (PMID 34898046, 2022). "This was a single‐center retrospective analysis of 4994 cancer patients who underwent tissue or blood genomic profiling, including CDK12 assessment, conducted as part of routine care from December 2012 to January 2020." (PMID 34898046, 2022). "We aimed to characterize CDK12 alterations across all cancer types through real‐world clinical‐grade sequencing." (PMID 34898046, 2022). "CyclinK degradation significantly enhanced inhibitors’ activity to suppress the function of CDK12 in cancer cells." (PMID 36145262, 2022). "For example, we found that CDK12 is essential in ~ 30% of cancer cell lines with average effects that were similar to those of CDK4 and CDK6." (PMID 36577800, 2022).
cancer (continued). "CDK7 inhibitors are being investigated as anti-cancer drugs, and CDK12/13 inhibitors are used in the treatment of a variety of cancers." (PMID 36299580, 2022). "Although the toxicity of THZ531 on normal cells has not been documented yet, all these studies, including ours, emphasize on the importance of CDK12 inhibitors and their potential in cancer therapeutics." (PMID 35163134, 2022). "Given its role in human cancers and regulation of genome stability, CDK12 is currently being studied as a potential therapeutic target." (PMID 34898046, 2022). "We aimed to characterize the clinical features of CDK12‐altered tumors utilizing a pan‐cancer database of patients undergoing clinical‐grade genomic profiling." (PMID 34898046, 2022). "The work presented here clearly suggests that sdRNA-A24 overexpression can likewise significantly reduce CDK12 expression resulting in a more metastatic cancer phenotype." (PMID 35455981, 2022). "Our study demonstrates that CDK12‐altered cancers have a prevalence of 0.88%, which is consistent with previously published reports on CDK12 genomic alterations." (PMID 34898046, 2022). "For example, this was the case with CDK12, which is essential in ~ 30% of cancer cells, and AFF3 which is essential in just a few cells." (PMID 36577800, 2022). "Other CDK inhibitors such as CDK12/13 inhibitors were also reported to induce immune death in different cancers." (PMID 35756622, 2022). "The mutational load in cancer-related genes between naïve and primed appears to be largely similar, if not higher in primed hPSC, where additional point mutations were identified in the cancer-related genes EGFR, PATZ1, and CDK12." (PMID 34831467, 2021). "CDK12 is overexpressed in a variety of cancers, including breast cancer, ovarian cancer, prostate cancer, and gastric cancer, making it a viable cancer target." (PMID 34771669, 2021). "CDK12 has crucial functions in gene expression, proliferation and genome stability, and is a target for anti-cancer therapy." (PMID 33764436, 2021). "CDK12, as an important factor regulating the cell-cycle process, is commonly involved in the growth of cancer cells." (PMID 33628849, 2021). "In vitro and in vivo functional experiments showed that knockdown of CDK12 inhibited cancer cell proliferation and colony formation and promoted apoptosis." (PMID 33628849, 2021). "Regarding specific cancer-associated genes, the CYT-high subgroup had more CNAs, including gains in NF1, CDK12, ERBB2, RARA, MDM4 and MYC; and losses in BRCA1, CD274 and APC." (PMID 34316699, 2021). "Short‐term inactivation of CDK12 – an essential gene in mammals – is deleterious for cancer cells and exposes them to vulnerability towards several anticancer agents, particularly those impinging on the DDR." (PMID 34092037, 2021). "The recently discovered SR-4835 (a selective dual inhibitor of CDK12/CDK13) exhibits excellent anti-cancer therapeutic effects, especially when combined with PARP inhibitors (DNA-damaging chemotherapy) or anti-PD-1 (checkpoint inhibition)." (PMID 34513922, 2021). "SEs regulate specific gene expression programs to sustain fundamental cell biology, including key lineage-specific oncogenes that control the cancer cell state, which is highly relevant to the characterization of CDK12-ISTs." (PMID 34315855, 2021). "The role of CDK12 in human cancer was first indicated in high-grade serous ovarian cancer (HGSOC), a disease characterized by a relatively high frequency of BRCA mutations, discovered by the Cancer Genome Atlas (TCGA) project." (PMID 32451425, 2020). "The transwell and metastasis assay results showed that CDK12 reduced cancer cell migration and the number of lung metastatic nodules." (PMID 32489449, 2020). "Inhibition of CDK12 by THZ531 can induce anti-proliferation of cancer cells by inducing apoptosis (IC50 of 50 nM in Jurkat cells), presumably due to transcriptional stress, similar to its predecessor, THZ1." (PMID 32451425, 2020).
cancer (continued). "Currently, CDK12 attracted more attentions in PARPi resistance, due to its inactivating somatic alterations were recurrently observed in various cancers." (PMID 32563252, 2020). "In summary, the inhibition of CDK12 seems to be a promising tool for the treatment of various MYC-dependent cancers." (PMID 34316683, 2020). "Here, we introduce the characteristics of CDK12, summarize the current advances of its biological functions and highlight its role in human cancer." (PMID 32570740, 2020). "In line with the concept of transcriptional addiction, CDK12 as a transcriptional regulator of DNA damage and replication genes can improve the fitness of cancer cells, as they are often substantially dependent on the DNA repair system." (PMID 34316683, 2020). "Loss of CDK12 function causes defective expression of DNA damage response (DDR) genes, which eventually results in genome instability, a hallmark of human cancer." (PMID 32451425, 2020). "Recently, it was found that a high level of CDK12 in various human cancers characterized by uncontrolled cell proliferation indicates the important regulatory role of CDK12 in cell proliferation." (PMID 32570740, 2020). "In summary, CDK12 can inhibit cancer progression and metastasis by affecting cell proliferation and migration and inhibiting c-myc/β-catenin pathway expression and cancer stemness." (PMID 32489449, 2020). "This review addresses emerging studies to dissect the novel mechanisms of CDK12 in gene expression regulation and its roles in human cancer and consider its potential clinical applications as a biomarker and cancer therapeutic target." (PMID 32451425, 2020). "Here, we summarize the current knowledge of CDK12, and review the research advances of CDK12′s biological functions, especially its role in human cancers and as a potential target and biomarker for cancer therapy." (PMID 32570740, 2020). "Evidence shows that CDK12 is not only a biomarker but also a potential therapeutic target of cancer." (PMID 32570740, 2020). "Our data demonstrated that CDK12 promoted cancer proliferation, migration and metastasis through the c-myc/β-catenin pathway." (PMID 32489449, 2020). "Since the mutation or amplification of CDK12 is closely related with tumorigenesis, CDK12 becomes an attractive therapeutic target for cancer treatment." (PMID 32570740, 2020). "Recently, increasing evidence demonstrates the important role of CDK12 in various human cancers, illustrating it as both a biomarker of cancer and a potential target for cancer therapy." (PMID 32570740, 2020). "Considering that CDK12 plays an important role in regulating transcription elongation and maintenance of genome stability, CDK12 aberrations are found in various types of cancer." (PMID 32570740, 2020). "Overall, our study has important implications for understanding the CDK12 cellular function, origins of CDK12‐specific genome instability phenotype, and in longer term for the development of CDK12‐specific cancer therapy." (PMID 31347271, 2019). "CDK12 is a kinase associated with elongating RNA polymerase II (RNAPII) and is frequently mutated in cancer." (PMID 31347271, 2019). "In this review, we discuss current knowledge concerning the role of CDK12 in ovarian and breast tumorigenesis and the potential for chemical inhibitors of CDK12 in future cancer treatment." (PMID 29090014, 2017). "Recently developed CDK12 inhibitors constitute not only powerful research tools but also promising anti-cancer drugs." (PMID 29090014, 2017). "In summary, CDK12 inhibitors show promise as anti-cancer drugs, either as a stand-alone treatment or in combination with other compounds such as PARP1/2 inhibitors." (PMID 29090014, 2017). "This adaptive equilibrium may explain the limited clinical efficacy of PARP inhibitor monotherapy in some CDK12-mutant cancers and underscores the need for combinatorial or dual CDK12/13-targeted approaches." (PMID 41491919, 2026).